SNHG1 (small nucleolar RNA host gene 1)
Diseases named in the same sentence as SNHG1 in open-access papers (continued):
Sharing a sentence is not in itself a finding about the gene and the disease.
cancer (continued). "In the present study, we found that SNHG1 expression level was higher in HCC tissues and cancer cell lines and was a poor prognosis marker in HCC, which is consistent with previous reports." (PMID 34917510, 2021). "Herein, we provided the first evidence to show that the METTL3/SNHG1/miR-140-3p/UBE2C axis plays a crucial role in cancer progression and the immune response in human pan-cancer." (PMID 34858987, 2021). "We also investigated commonly shared lncRNAs between COAD and READ (CRCs) and found the presence of MAGI2-AS3, GAS5, SNHG1, KCNQ1OT1, SNHG20, and MIR17HG in both cancers." (PMID 35140741, 2021). "First, to confirm the regulatory pattern of SNHG12 in ESCC, we found that SNHG1, SNHG7, and SNHG12 were three upregulated lncRNAs in ESCC tissues through Cancer RNA‐Seq Nexus analysis." (PMID 32239639, 2020). "This study suggests that SNHG1 inhibits the proliferation and metastasis of PCa cells by binding EZH2, and promotes the apoptosis and autophagy of cancer cells." (PMID 33194612, 2020). "Using “starBase” algorithm, four miRNAs were identified to be the downstream molecules of SNHG1 (CLIP data: strict stringency; degradome data: high stringency; pan-cancer: at least two cancer types)." (PMID 32536864, 2020). "The lncRNA small nucleolar RNA host gene 1 (SNHG1), located at 11q12.3, has been reported as an oncogene and a prognostic indicator in some human cancers." (PMID 31189920, 2019). "No other clinicopathologic or demographic variable, including sex, BMI group, tumor location, TNM stage, chronic disease status, or family history of cancer, showed a significant relationship with the expression of RUSC1-AS1, SNHG17, PABPC1L, or SNHG1 (all p > 0.05)." (PMID 41357316, 2025). "Notably, SP1 binds to the SNHG1 promoter region, enhancing SNHG1 transcriptional activity and forming a positive feedback regulatory loop involving SP1/SNHG1/miR-199a-5p, which further amplifies pro-cancer signaling." (PMID 41234719, 2025). "Moreover, SNHG1 emerges as an important regulator in mediating metabolic reprogramming in HCC cells, modulating the metabolism of FA, iron, and glucose to enhance cancer cell survival in hostile environments." (PMID 39200161, 2024). "Based on TCGA data, an in-depth evaluation of the expression of SNHG1 among different cancers shows a significantly increased expression of this lncRNA species in HCC tissues compared to healthy liver tissues, as well as in other forms of cancer." (PMID 39200161, 2024). "SNHG1 also promotes glycolysis in HCC cells by facilitating the expression of PKM2, a kinase with a multitude of interacting molecular partners, which enhances cancer metabolism by promoting the metabolic reliance of cancer cells on glucose." (PMID 39200161, 2024). "This suggests unexplored mechanisms through which SNHG1 might contribute to metabolic reprogramming in HCC and hints at new research endeavors in the field of lncRNAs and cancer." (PMID 39200161, 2024). "Exosomal LINC00265, LINC00467, UCA1, and SNHG1 may act as promising cell-free biomarkers for AML diagnosis and treatment monitoring and provide a new frontier of liquid biopsy for this type of cancer." (PMID 36276083, 2022). "Our observations prove that exosomal LINC00265, LINC00467, UCA1, and SNHG1 may act as novel cell-free indicators for AML diagnosis and treatment monitoring and provide a new frontier of liquid biopsy for this type of cancer." (PMID 36276083, 2022). "Notably, SNHG1 and SNHG7 not only regulated many FA metabolism related-genes, but also mediated cancer cell ferroptosis." (PMID 36195833, 2022). "SNHG1 is a small nucleolar RNA host gene 1, a novel lncRNA that is increased in various human cancers, but there is no data regarding OSCC." (PMID 33643897, 2020).
cancer (continued). "Former studies illustrated that lncRNA could regulate certain gene expressions in human cancers, and SOX9 has been revealed to be regulated in several lncRNA in cancers such as lncRNA MALAT1 and SNHG1." (PMID 31402556, 2019). "The combined results indicated that the elevated SNHG1 expression level was significantly predicted poor OS (HR = 2.06, 95% CI: 1.69–2.52, P < 0.01) and PFS (HR = 2.78, 95% CI: 1.69–4.55, P < 0.01) in various cancers." (PMID 31391030, 2019). "In recent years, a numbers of lncRNAs [LncRNA uc.372, SNHG16, SNHG1, or MALAT1] were observed to negatively regulate miR-16 family member expression and played a role in pathogenesis of cancers." (PMID 31316397, 2019). "The result of GSE20842 demonstrated that SNHG1 expression was 1.77-fold higher in cancer tissues as compared with the non-tumor rectum tissues (*, p=1.25E-15)." (PMID 29416759, 2018). "Correlation analysis of the dataset GSE76297 (92 pairs of cancer and 91 normal tissue samples) from the Molecular Signature Database suggested that CDKN1A was substantially negatively correlated with EZH2 and SNHG1." (PMID 29970899, 2018). "Moreover, previous studies indicated that lncRNA SNHG1 could bind to and regulate the expression of DNMT1 in certain diseases, such as cancers." (PMID 34854215, 2022). "Based on previous observations, we provide a strong evidence that SNHG1 interacts with RNA-binding protein hnRNPL to activate EMT pathway, promoting the malignant progression of PCa, which is expected to provide a comprehensive understanding of the way SNHG1 acts on cancers." (PMID 33542227, 2021). "Besides, to explore therapeutic value of the key nodes in other cancers, we found that SERPINE1/hsa-mir-145/SNHG1 axis mainly expressed in alimentary tract malignancies but not other cancers." (PMID 33552958, 2020). "Interestingly, plasma SNHG1 expression levels correlated also with tumor size, TNM staging, and α-fetoprotein levels, demonstrating its potential of being a reliable biomarker for the diagnosis of this cancer." (PMID 31416190, 2019). "We found that SNHG1 exhibited a significant negative correlation with the expression of miR-140-3p and a positive correlation with the expression of UBE2C in the pan-cancer analysis." (PMID 34858987, 2021).
tumor (105 papers, 2015 to 2026). "SNHG1 expression was negatively associated with ER positivity, PR positivity, and combined ER+/PR+ status, consistent with its observed upregulation in tumor samples." (PMID 41283331, 2025). "In conclusion, SNHG1 has the potential to become an emerging tumor diagnostic target and can be used as a prognostic biomarker or therapeutic target." (PMID 37684619, 2023). "Results of gain and loss of function shown that lncRNA SNHG1 promoted PCa cell proliferation and migration in vitro, and loss-of SNHG1 inhibited vivo tumor growth, suggesting that SNHG1 is essential in PCa progression." (PMID 33542227, 2021). "SNHG1 expression is associated with unfavorable overall survival and tumor recurrence in patients with COAD." (PMID 32727450, 2020). "The multivariate logistic regression analysis showed that tumor stage (P < 0.0001) and expression of lnc-SNHG1 (P = 0.01) were independent risk factors associated with the chemoresistance of serous EOC." (PMID 33302997, 2020). "Our data showed that SNHG1 expression in NSCLC tissues was significantly associated with larger tumor size, advanced TNM stage and lymph node metastasis (P < 0.05)." (PMID 28147312, 2017). "The potential of these genes to distinguish between tumor and benign samples was further assessed using ROC analysis, revealing favorable AUC values, sensitivity, and specificity for all genes, except for SNHG1 and SNORD94, which showed suboptimal diagnostic performance." (PMID 41283331, 2025). "Our results agree with this study and suggested that downregulation of miR-376a might underlie the tumor-promotive action of SNHG1." (PMID 34095464, 2021). "Moreover, the promoted SNHG1 expression was also associated with tumor progression ((III/IV vs. I/II: HR = 1.89, 95% CI: 1.53–2.34, P < 0.01)." (PMID 31391030, 2019). "Moreover, the promoted SNHG1 level was also associated with tumor progression ((III/IV vs. I/II: HR = 1.89, 95% CI: 1.53–2.34, P < 0.01) and (III vs. I/II: HR = 1.88, 95% CI: 1.33–2.66, P < 0.01))." (PMID 31391030, 2019). "High SNHG1 expression is associated with tumor progression and poor prognosis." (PMID 30266084, 2018). "So, that is why we think that the effects of SNHG1 on tumor cell proliferation and metastasis might be associated with β-catenin regulation." (PMID 29340086, 2017). "Meanwhile, exosomal SNHG1 has also been highlighted to act as a ceRNA, where it has the potency to competitively bind to tumor-suppressive microRNAs (miRNAs)." (PMID 41507135, 2026). "In this paired analysis of 43 CRC patients, we found consistent upregulation of PABPC1L, SNHG17 and SNHG1 in tumor tissues relative to ANT samples, while RUSC1-AS1 showed a non-significant trend toward increased expression." (PMID 41357316, 2025). "Studies have found that SNHG1 is abnormally expressed in various tumor tissues and cells and is closely related to tumor proliferation, invasion, and metastasis." (PMID 41346419, 2025). "SNORD15B, SCARNA3, and RNU2-1 snRNA also appear to have tumor-suppressive potential, whereas the evidence for oncogenic roles of SNHG1 and SNORA68 was less convincing." (PMID 41283331, 2025). "HNSCC: SNHG1 inhibition ↑PARP6 → suppresses tumor growth/migration; HCC: Low PARP6 → HDM2‐mediated XRCC6 degradation → ↑Wnt signaling → promotes progression." (PMID 40904702, 2025). "SNHG1 knockdown suppressed tumor growth and reversed sunitinib resistance and autophagy of RCC cells." (PMID 38851811, 2024). "Immunohistochemical staining further revealed a significantly upregulation of the proliferation marker Ki67 in SNHG1-overexpressing tumor tissues, confirming that SNHG1 overexpression enhances BMIBC tumorigenicity in vivo." (PMID 38365726, 2024). "Regarding tumor size, larger tumors significantly correlate with higher expression of SNHG1, as tumors greater than 5 cm exhibit higher expression of SNHG1 as compared to those smaller than 5 cm." (PMID 39200161, 2024).
tumor (continued). "Of the 22 members of the SNHG family, SNHG1 is crucial and functions as an oncogene that promotes tumor growth." (PMID 37684619, 2023). "SiRNA-mediated knockdown of SNHG1 decreased tumor progression indicating that SNHG1 promotes tumor immune escape by stimulating Treg cell differentiation." (PMID 37346034, 2023). "T24T cells over-expressing SNHG1 had a markedly increased ability to form stem-cell-like tumor spheres compared to their control counterparts, while SNHG1 knockdown blocked this effect." (PMID 36077697, 2022). "SNHG1 led to abnormal transcription of genes by altering chromatin structure, thus promoting tumor growth." (PMID 36087568, 2022). "SNHG1 expression was upregulated in hepatocellular carcinoma cells, which promoted tumor growth and inhibited apoptosis by activating Akt signaling pathway." (PMID 36087568, 2022). "Compared with normal samples, GSE7476 and GSE65635 displayed high expression of SNHG1 in tumor samples." (PMID 36087568, 2022). "Functional investigation showed that SNHG1 promoted tumor proliferation, migration, and tumorigenesis." (PMID 36087568, 2022). "The small nucleolar RNA host gene 1 (SNHG1) is a novel oncogenic long non-coding RNA (lncRNA) aberrantly expressed in different tumor types." (PMID 36130928, 2022). "It is well-established that long noncoding RNA small nucleolar RNA host gene 1 (lncRNA SNHG1) is involved in tumor stage, size and overall survival." (PMID 36230661, 2022). "C (six mice per group), the knockdown of SNHG1 inhibited tumor growth significantly compared with control group." (PMID 34917510, 2021). "Our results highlight the benefit of utilizing multiple datasets to understand the functional potential regulatory networks of SNHG1 and the role of SNHG1 in tumours." (PMID 33499863, 2021). "In one study, scientists compared PCa specimens and specimens of adjacent non-tumour tissue and found that the expression level of SNHG1 was much higher in the former than in the latter." (PMID 33968736, 2021). "The higher expression level of SNHG1 was dramatically correlated with tumor metastasis and patient survival." (PMID 33542227, 2021). "lncRNA SNHG1 had been reported to be highly expressed in NSCLC, while the overexpression of lncRNA SNHG1 has been reported to enhance tumor cell metastasis and further aggravate NSCLC." (PMID 33816782, 2021). "Our study also determined the tumor-suppressing function of SNHG1 knockdown at molecular levels, corresponding to reductions in MMP-2, MMP-9, Bcl-2, and N-cadherin and elevations in Bax and E-cadherin." (PMID 34095464, 2021). "Downregulation of both LMNB2, the target of miR-326 in HCC, and SNHG1 inhibited tumor proliferation and growth in vitro and in vivo." (PMID 34917510, 2021). "Given the role of SNHG1 in vitro, we investigated if SNHG1 knockdown suppressed tumor growth in vivo." (PMID 34806925, 2021). "Here we reported that lncRNA SNHG1 functioned as a modulator of M2 macrophage polarization and regulated tumor growth and angiogenesis." (PMID 34618681, 2021). "SNHG1 knockdown reduced tumor volume and weight and lung metastasis, while the restoration of Snail reversed those reductions." (PMID 34095464, 2021). "Expression levels of SNHG1 were determined in the PCa primary tumor tissues and its correlations with clinicopathological parameters were also analyzed." (PMID 33542227, 2021). "In one study, SNHG1 was found to be greatly upregulated in RCC cells relative to surrounding non-tumour cells, and SNHG1 inhibition was shown to block the EMT, thereby reducing tumour cell growth and invasion." (PMID 33968736, 2021).
tumor (continued). "SNHG1 expression levels were increased in BC tissues compared with that observed in normal bladder tissues in the subgroup analyses, including tumour stage and nodal metastasis status." (PMID 32885590, 2020). "The SNHG1 knockdown group showed significantly reduced tumor growth in the lungs compared with the NC control group." (PMID 32497022, 2020). "They found that the high expression level of lnc-SNHG1 was closely related to large tumor size, poor differentiation, and aggressive stage, suggesting the poor prognosis of patients with HCC." (PMID 33302997, 2020). "The clinical features including tumor stage, histological grade, nodal status, metastasis, tumor size, and expression levels of lnc-SNHG1 and miR-216b-5p were included in the model." (PMID 33302997, 2020). "The in vivo experimental results also indicated that SNHG1 down‐regulation hampered the tumour growth and metastasis of BC cells." (PMID 32885590, 2020). "The high expression level of lnc-SNHG1 significantly correlated with tumor stage, histological grade, nodal status, metastasis, and chemoresistance except tumor size." (PMID 33302997, 2020). "In osteosarcoma, SNHG1 promotes cell proliferation, tumor growth, invasion, and EMT by sponging miR-326, resulting in overexpression of NOB1 [NIN1 (RPN12) Binding Protein 1 Homolog]." (PMID 32318335, 2020). "In contrast, overexpression of SNHG1 resulted in opposite effects, suggesting that SNHG1 can also act as an oncogenic ceRNA via sponging the tumor-suppressive miR-140." (PMID 32331331, 2020). "IHC results indicated that HK2 expression was remarkably down‐regulated by SNHG1 knockdown in xenograft tumours formed from a stable EJ cell line." (PMID 32885590, 2020). "The lnc-SNHG1 high expression showed a significant correlation with tumor stage, histological grade, nodal status, metastasis, and chemoresistance except tumor size." (PMID 33302997, 2020). "The IHC results also confirmed that the positive expression of Ki67 in the tumor tissue decreased after interference with SNHG1, while the positive expression of Ki67 increased after interference with SNHG1 and overexpression of EZH2." (PMID 33194612, 2020). "Small nucleolar RNA host gene 1 (SNHG1) is a relatively novel lncRNA that is involved in the development of multiple human tumours." (PMID 31189920, 2019). "In our work, we found that knockdown of SNHG1 leads to an increase in the expression of miR-101, a tumor suppressor." (PMID 31615767, 2019). "Further investigations reveal that SNHG1 contributes to the progression of AML by negative regulation of a tumor suppressor, miR-101." (PMID 31615767, 2019). "In the studies of several malignant tumor tissues, it has been found that small nucleolar RNA host gene 1(SNHG1), is abnormally high expressed which is closely related to malignant progression and poor prognosis of tumor." (PMID 30728054, 2019). "Both public microarray data and a cohort study discovered that SNHG1 levels are significantly increased in HCC tissues, and the high expression of SNHG1 is positively associated with tumor size." (PMID 31480503, 2019). "While upregulation of SNGH7 inhibits apoptosis and promotes the proliferation of cancerous gastric cells, SNHG1’s overexpression is correlated with advanced colorectal cancer stage and tumor recurrence." (PMID 30654440, 2019). "Compared with the control, the weights and volumes of tumours in the SNHG1 downregulation group were decreased, while the SNHG1 plasmid caused an increase in tumour weight and volume." (PMID 31189920, 2019). "Here, for the first time, we verified that SNHG1 exhibited tumour‐promoter effects in NPC by regulating cell invasion and migration." (PMID 29575772, 2019). "It was shown in the present study that miR‐145‐5p functioned as a tumour suppressor, whereas SNHG1 reversed the antitumour effect of miR‐145‐5p by direct modulating miR‐145‐5p, thus promoting cell propagation and aggressiveness." (PMID 29575772, 2019).